CASP1 (caspase 1)
Diseases named in the same sentence as CASP1 in open-access papers (continued):
Sharing a sentence is not in itself a finding about the gene and the disease.
diabetes (75 papers, 2007 to 2025). "The administration of puerarin to a model of STZ-induced diabetes caused the inhibition of caspase 1-mediated pyroptosis, which is involved in the progression of diabetic nephropathy." (PMID 41020857, 2025). "ROS and hyperglycemia associated with diabetes activate NLRP3 oligomerization which triggers the activation of caspase-1." (PMID 37056985, 2023). "The results showed that the expression levels of NLRP3, caspase 1, IL-1β and IL-18 were increased in CD38flox mice with diabetes compared with the normal group, whereas CD38 deficiency significantly decreased the expression of these genes at the mRNA level." (PMID 37958991, 2023). "Spironolactone also reduced active caspase-1-positive macrophages in db/db mice, events that contribute to diabetes-associated vascular changes." (PMID 31817997, 2019). "ROS has been implicated in caspase-1 activation during various patho-physiological conditions like diabetes; ROS production was essential for inflammasome formation by glucose, IPP and fatty acids." (PMID 22295065, 2012). "Moreover, caspase-1-dependent pyroptosis induced by ROS-mediated NLRP3 inflammasome activation is an important factor for the diabetes-associated increased sensitivity to MI/R and exacerbated MI/R injury." (PMID 29062465, 2017). "Also, the blockade of the Casp-1/IL-1β pathway may prevent Müller cell loss induced by diabetes, indicating that the pyroptotic process may be responsible for Müller cell death." (PMID 34877938, 2021). "Our results show for the first time that DAPA plays an important role in the treatment of diabetes-related liver fat deposition by targeting NLRP3-Caspase-1 axis-mediated cell pyroptosis." (PMID 40136402, 2025). "The evidence from animal models of diabetes shows that neuronal death is a vital factor leading to brain injury, and caspase-1 inhibition mitigates brain ischemic injury-induced neuronal death." (PMID 37697221, 2024). "We have previously shown that diabetes leads to the activation of caspase-1 and IL-1β production and that blocking downstream caspase-1/IL-1β/IL-1R1 signaling using IL-1R1 knockout mice prevented the formation of acellular capillaries and Müller cell death." (PMID 39483336, 2024). "Using the IL-1R1−/− mice we identified that diabetes-induced caspase-1 activity progresses from an IL-1R1 independent mechanism to an IL-1R1 dependent mechanism throughout disease progression." (PMID 39483336, 2024). "At 20 weeks of diabetes, caspase-1 activity was increased by 30.2% ± 3.8% in the retinas of diabetic WT mice compared to non-diabetic WT mice." (PMID 39483336, 2024). "VX-765, a specific inhibitor targeting CASP-1, demonstrated a mitigating effect on pyroptosis in both ketamine-induced renal injury and diabetes." (PMID 38229085, 2024). "Increased renal CASP1 expression and activity are demonstrated in both animal models and human studies of diabetes." (PMID 38766319, 2024). "After 10 weeks of diabetes, caspase-1 activity was significantly increased in both diabetic WT and diabetic IL-1R1−/− mice by 59.6% ± 15.3% and 33.2% ± 9.8% respectively compared to non-diabetic mice." (PMID 39483336, 2024). "Regarding NF-κB, it has also been observed to increase its expression in diabetes, converting pro-caspase-1 to mature caspase-1 and facilitating pyroptosis of type I alveolar epithelial cells through Toll-like receptors (TLRs) and NLRP3 pathways." (PMID 37964954, 2023). "Specifically, a reduction in lncRNA-Fendrr led to decreased levels of NLRC4, ASC, pro-caspase-1, and caspase-1-mediated pyroptosis in a diabetes-cerebral I/R BV-2 cell model." (PMID 38002304, 2023). "The same outcome was obtained when the authors used the caspase-1/IL-1β pathway to prevent diabetes-induced MC death in vivo." (PMID 37418795, 2023).
diabetes (continued). "When SGLT2 inhibitors were provided, the same group showed diabetes-associated increases in inflammation-suppressed NLRP3 inflammasome activity as well as lower mRNA levels of ASC, IL-6, IL-1b, TNF-a, and caspase-1." (PMID 37566054, 2023). "It is activated under diabetes conditions that promotes caspase-1 autocleavage, and the maturation of pro-IL-1β/18, IL-1β, and IL-18 is secreted into the extracellular space to participate in the subsequent inflammatory response." (PMID 36111168, 2022). "MCC950 improved cardiac contractility, reduced cardiac hypertrophy and the fibrotic area, inhibited NLRP3 and caspase-1 expression, and suppressed inflammation in mice with MI and diabetes." (PMID 36320147, 2022). "Aerobic exercise is believed to be a promising intervention to reduce the expressions of ROS, NF-κB, NEK7, NLRP3, ASC, Caspase-1, IL-1β, and other inflammatory factors, and improves diabetes-induced inflammation and reduces insulin resistance." (PMID 36248820, 2022). "In diabetes patients significantly higher levels of circulating gp130 and higher expression of caspase-1 in EAT (p < 0.05, both) were found, and patients with previous myocardial infarction had higher circulating levels of IL-18 (p = 0.020)." (PMID 36644557, 2022). "Zoledronic acid increases the expression of IL-1β in an NLRP3/caspase-1-dependent manner in LPS-primed BMDMs from mice with diabetes mellitus, and NLRP3 inhibitors improve oral wound healing and suppress osteonecrosis of the jaw in these mice." (PMID 34177950, 2021). "Our study found that the restraint of lncRNA-Fendrr markedly reduced NLRC4, ASC, pro-caspase-1, and caspase-1 mediated pyroptosis in BV-2 cell model of diabetes-cerebral I/R." (PMID 33858325, 2021). "Previous studies found the overexpression of NLRP3, caspase-1, and IL-1 in the heart of rats with diabetes." (PMID 35145423, 2021). "Compared with a healthy person, caspase-1 cleavage and IL-1β maturation are elevated in patients with type 2 diabetes mellitus (T2DM), which can be significantly suppressed by metformin." (PMID 33980323, 2021). "In summary, our data suggested that empagliflozin protects the pancreatic tissues from diabetes mellitus-induced injury by downregulating the NLRP3/caspase-1/GSDMD pyroptosis-related inflammasome pathway." (PMID 34823419, 2021). "Diabetes, a sterile inflammatory condition, is related to increased pyroptosis, characterized by increased caspase-1, IL-1β, and GSDMD in skeletal muscle." (PMID 34360821, 2021). "This study elucidates the detailed mechanism of HG-initiated HASMC calcification through NLRP3/caspase 1/IL-1β inflammasome and indicates a potential therapeutic role of 6-shogaol in vascular calcification complication of diabetes." (PMID 31938471, 2020). "After treatment with metformin in diabetes-susceptible B4 cells, the expression of nutrition excess-induced innate immunity/inflammasome molecules was ameliorated, including MDA5, NLRP3, caspase-1, and IL-1β." (PMID 32849261, 2020). "Animal experiments with NOD caspase-1(–/–) mice revealed reduced IL-1 levels, but an unchanged incidence of diabetes and sensitivity to streptozotocin compared with wild type NOD mouse models." (PMID 32973739, 2020). "In the diabetes group, we observed a tendency towards an increase in the caspase-1 level, while glyburide treatment (1 μM, 24 h) diminished this factor in this group (p < 0.05)." (PMID 31197747, 2019). "Caspase-1 is involved in various types of diseases, including hepatic injury, cancers, and diabetes-related complications." (PMID 29440460, 2018). "When compared with the control rats, diabetic rats showed elevated mRNA and protein levels of NLRP3, ASC, caspase-1 and IL-1β beginning at 4 or 8 weeks of diabetes (all p<0.01)." (PMID 25136835, 2014). "The effect of epifamin on free radical processes, the activity of caspase-1 and-3, aconitate hydratase and citrate content in rat’s liver atexperimentally induced type 2 diabetes mellitus (T2DM) was studied." (PMID 24455191, 2013).
diabetes (continued). "The effect of diabetes on the expression of various inflammatory (TNFα, IL-6, IL-1β and IFNγ) and apoptosis markers (caspase-1) was also evaluated in intact retinas from wt, ApoE−/−, TNFα−/− and ApoE−/−/TNFα−/− mice." (PMID 20856927, 2010). "In the retinas of diabetic wt mice, we also found significantly increased levels of TNFα, IL-6 and IL-1β mRNA expression and a tendency to increased IFNγ and caspase-1 mRNA, indicating some degree of local inflammation after 8 weeks of diabetes." (PMID 20856927, 2010). "DAPA may improve liver glucose and lipid metabolism and function in diabetes model mice by inhibiting NLRP3-Caspase-1 signal transduction and regulating mitochondrial oxidative stress." (PMID 40136402, 2025). "The overall increase of caspase-1 activity levels at 20 weeks of diabetes compared to 10 weeks of diabetes (p = 0.004) was slightly due to increased background fluorescence that excited and emitted at the same wavelength as the caspase-1 substrate and mostly due to aging." (PMID 39483336, 2024). "Our in vivo results demonstrate that caspase-1 activation progresses from an IL-1R1 independent mechanism at 10 weeks of diabetes to an IL-1R1 dependent mechanism at 20 weeks indicating that feedback through IL-1R1 is crucial for sustained caspase-1 activity in retinas of mice." (PMID 39483336, 2024). "This could explain the long duration of diabetes required for caspase-1 activity to become dependent on IL-1β feedback in vivo." (PMID 39483336, 2024). "Diabetes is considered accelerated aging and aging is promoted by increased inflammatory events such as the activation of caspase-1." (PMID 39483336, 2024). "This suggests that the P2X7R/NLRP3/caspase-1 implicated pyroptosis and inflammatory scenario may serve as a potential target for the management of comorbid DNP and MDD in diabetes." (PMID 38256257, 2024). "Moreover, caspase-1, which is elevated in diabetes, cleaves SIRT1 to upregulate activator protein-1 (AP-1), ultimately leading to an increase in VCAM-1 of endothelial cells, promoting adherence of monocytes." (PMID 37964954, 2023). "However, to the best of our knowledge, there was no study that reported the effect of ST on the hepatic NLRP3, caspase-1, and IL-1β in diabetes rat models induced by STZ, which emphasizes the importance of this study." (PMID 38131990, 2023). "They presented in patients with morbid obesity and type 2 diabetes mellitus with normal glucose tolerance that caspase-1 levels are normalised after weight loss, whereas IL-1β is normalised only in people without diabetes mellitus." (PMID 36231470, 2022). "The expression of NLRP3/IL-1β/caspase-1 has been observed in patients with diabetes, myocardial infarction, arrhythmia, and cardiac hypertrophy, and some agents can improve the symptoms of cardiovascular disease in patients by inhibiting the occurrence of pyroptosis." (PMID 35647057, 2022). "In other studies, it was shown that MCC950 could effectively alleviate diabetes-induced renal damage by inhibiting the NLRP3/Caspase-1 pathway, which may be a potential therapeutic strategy for preventing the progression of diabetic nephropathy." (PMID 35566282, 2022). "Moreover, high expression of NLRP3 and caspase-1 was found in cardiac fibrosis tissue of rats with diabetes." (PMID 35145423, 2021). "NLRP3, caspase-1, IL-1β, and IL-18 were minimally expressed in normal glomerular tissues, but were significantly up-regulated in diabetic apoE (-/-) and apoE (-/-) mice, with more prominent changes in diabetes apoE (-/-) mice." (PMID 28708885, 2017). "Caspase 1 may be more important than caspase 3 in podocyte apoptosis, at least, in the condition of diabetes." (PMID 28228761, 2017). "In wt mice, diabetes resulted in a clear increase in TNFα, IL-6 and IL-1β mRNA expression levels (p<0.01, p<0.01 and p<0.05, respectively) and in a tendency to higher IFNγ and caspase-1 mRNA levels (n.s.)." (PMID 20856927, 2010).
diabetes (continued). "Additionally, the protective effect of N-acetylcysteine (NAC) in diabetes-related ocular surface damage may be attributed to inhibition of the ROS/NLRP3/Caspase-1/IL-1β pathway." (PMID 35656447, 2022). "Our in vitro study confirmed that empagliflozin reduced the activation of NLRP3 and the expression of pyroptosis-related inflammasomes in pancreatic β cells under a high glucose environment, suggesting that the NLRP3/caspase-1/GSDMD pathway may be a potential therapeutic target for diabetes." (PMID 34823419, 2021). "This study evaluated whether empagliflozin (EMPA) protects the pancreas from diabetes mellitus-induced injury by downregulating the nucleotide-binding oligomerization domain-like receptor protein 3 (NLRP3)/caspase-1/Gasdermin D (GSDMD) pyroptosis-related inflammasome pathway in vitro and in vivo." (PMID 34823419, 2021). "SIRT1 expression was found to be low in mice with STZ-induced diabetes, but puerarin increased SIRT1 expression, inhibited the activation of the NLRP3/caspase 1 pathway, reduced podocyte pyroptosis, and alleviated their renal inflammatory injury." (PMID 41020857, 2025). "It has been reported that miR-9-5p can mitigate diabetes by downregulating pyroptosis, which is coupled with reductions in IL-1β, IL-18, NLRP3, and Caspase-1." (PMID 38934781, 2024). "Diabetes triggered NLRP3, ASC, gasdermin-N, caspase-1, and collagen I expression and increased the number of TUNEL positive cells in myocardial tissue of ob/ob mice." (PMID 36320147, 2022). "In diabetes, the activation of NF-κB stimulates the transcription of NLRP3 and activation of the NLRP3 inflammasome, resulting in the cleavage of caspase-1, which increases the production of mature IL-1β and IL-18." (PMID 34997266, 2022). "Diabetes triggered NLRP3, ASC, gasdermin-N, caspase-1, and collagen I expression in myocardial tissue, and promoted an increase in the serum TNF-α, IL-1β, IL-6, and IL-18 levels." (PMID 36320147, 2022). "The activation of diabetes-mediated related factors such as TLR4, NLRP3, caspase-1, IL-1β, IL-18, and GSDMD-NT plays a vital role in the pathophysiology of DKD." (PMID 33692782, 2021). "Our previous study have also found that caspase-1-dependent pyroptosis induced by NLRP3 inflammasome activation contributed to diabetic myocardium and aggravated MI/R injury in diabetes." (PMID 30911553, 2019). "With diabetes, NLRP3 is stimulated by the ER stress and cleaves and stimulates caspase-1, leading to secretion and release of the pro-inflammatory cytokines IL-1β and IL-18." (PMID 30657794, 2019). "Previous reports have indicated that the executor caspase of pyroptosis (activated caspase-1), which is induced by the NLRP3 inflammasome, is increased in a diabetic rat model and plays an important role in the development of diabetic cardiomyopathy." (PMID 29062465, 2017). "PIO significantly attenuated the diabetes-induced activation of the NLRP3 inflammasomes and their downstream effectors, including caspase-1, IL-1β, and IL-18." (PMID 28708885, 2017). "Thus given inflammasome activation can impair several metabolically relevant signaling proteins such as Sirt1, additional studies are required to test whether specific inflammasome or caspase-1 inhibitors offer better therapeutic alternatives than IL-1β inhibition as treatment for diabetes." (PMID 23483669, 2013). "Furthermore, melatonin suppressed neuronal pyroptosis and enhanced autophagy induced by diabetes through reducing the levels of Beclin1, NLRP3, ATG12, caspase-1, GSDMD-N, and LC3 in vivo and in vitro." (PMID 37697221, 2024). "Accordingly, we hypothesized that NLRP3 dysregulation might affect pyroptosis in diabetic ED and evaluated pyroptosis markers (GSDMD, GSDMD-N, pro-caspase-1, cleaved-caspase-1, ASC, IL-1β, and IL-18)." (PMID 39014129, 2024).
diabetes (continued). "In this observation, quantitative analysis of fluorescence intensity showed that compared with the diabetes group, the average optical density of GSDMD in the SCU treatment group tended to decrease, supporting caspase-1 regulating GSDMD pathway has been involved in our observation." (PMID 37081038, 2023). "It is noteworthy that mice lacking caspase-1, despite having diminished IL-1 and IL-18 levels, demonstrated comparable diabetes incidence and streptozotocin sensitivity to regular mice." (PMID 37762961, 2023). "Chronic inflammation is an important pathophysiological factor leading to diabetes, which is manifested by higher levels of Nod-like receptor protein 3 (NLRP3), Caspase-1, Interleukin-1β (IL-1β), and various antiviral inflammatory cytokines, inducing a strong inflammatory response in the body." (PMID 36248820, 2022). "Therefore, 12 weeks of Tai Chi intervention can significantly decrease the expressions of NEK7, NLRP3, ASC, Caspase-1, GSDMD, IL-1β, and IL-18, while increasing the expression of irisin in pre-diabetes." (PMID 36248820, 2022). "At a minimum, caspase-1-mediated IL-1β production is not indispensable for diabetes development in NOD mice." (PMID 32973739, 2020). "Direct experimental evidence in mice models of diabetes is limited, with a study demonstrating elevation of TNFα mRNA in male C57Bl6 mice 5 months after induction of diabetes by STZ and another study showing activation of caspase-1/IL-1β signaling in retinas of diabetic mice." (PMID 20856927, 2010). "In addition, our data demonstrate that diabetes induced increased expression of NLRP3 inflammasome components pro-caspase 1 and NLRP3 were not significantly attenuated by MCC950." (PMID 35048962, 2022). "Activation of the diabetes-mediated pyroptosis-related inflammasomes, such as nucleotide-binding oligomerization domain-like receptor protein 3 (NLRP3), Toll-like receptor 4 (TLR4), caspase-1, interleukin (IL)-1β, and the IL-18 axis, plays an essential role in DKD lesions." (PMID 33692782, 2021). "Together with the observation that caspase 1, but not caspase 3, mediates podocyte injury in DN, these studies strongly suggest that high glucose or hyperglycemia may cause podocyte injury or death through an innate immune pathway involving NLRP3 in diabetes." (PMID 28228761, 2017). "Subgroup analyses showed that the post-ACS upregulation of NLRP3, caspase-1, and IL-1β was consistent across STEMI and NSTEMI presentations and was not significantly modified by diabetes status." (PMID 41598157, 2025).